CCR2 (C-C motif chemokine receptor 2)
Diseases named in the same sentence as CCR2 in open-access papers (continued):
Sharing a sentence is not in itself a finding about the gene and the disease.
cancer (continued). "The development of CCR2 inhibitors has brought positive results in cancer treatment, and multiple CCL2-neutralizing antibodies are being tested in clinical trials." (PMID 39003350, 2024). "CCL2 is a prognostic factor in HCC and suppression of CCL2/CCR2 axis can suppress TAMs toward M2 polarization and impair the progression of murine liver tumor model through induction of T cell-mediated anti-cancer immune reactions." (PMID 38997297, 2024). "MCP-1 operates by binding to its specific receptor CCR2, initiating signaling pathways that promote cancer cell proliferation and suppress immune responses 110-112." (PMID 39132165, 2024). "For more detailed analysis we selected activated CCL2 (also known as MCP-1) which encodes a ligand that binds and activates its cognate receptor CCR2, plays multifaceted roles in myeloid immune cells, and acts as an oncogene in some cancer types." (PMID 39689089, 2024). "It has been discovered that the interaction between CCL2 and CCR2 is an important signaling axis in cancer growth." (PMID 39201480, 2024). "CCR2 is critical for monocyte extravasation and migration and is needed for cell migration in models of cancer." (PMID 39545417, 2024). "These compounds highlight the ongoing advancements in targeting CCR2 to enhance cancer treatment outcomes." (PMID 39286635, 2024). "Other groups have shown that use of Ccr2–/– mice or CCR2 inhibitors in murine models also resulted in decreased disease progression in many cancer types." (PMID 38716730, 2024). "The chemokine CCL2 and its primary receptor CCR2 have garnered significant attention due to their involvement in cancer development." (PMID 38468260, 2024). "Cancer cells release CCL2 to recruit classical monocytes expressing its receptor CCR2 for the promotion of metastasis and resistance to immunosurveillance." (PMID 39545417, 2024). "CCL2 is a chemokine that attracts CCR2-expressing immune cells (e.g., inflammatory or classical monocytes) and is highly relevant for cancer development and poor outcomes." (PMID 38786066, 2024). "These conflicting perspectives highlight the need for more in-depth investigations to fully understand the multifaceted role of CCR2 in cancer biology." (PMID 38755605, 2024). "In the case of CCR2, inhibition of CCR2 was also effective in reducing cancer metastasis in preclinical models." (PMID 39169402, 2024). "Simultaneously, genes promoting anti-cancer efficacy such as Cd160, Cd244a, and Ccr2 were highly expressed while a relay gene of the NF-κB pathway, Card11, was suppressed in NK cells after CBL0137 treatment." (PMID 39518148, 2024). "Crosstalk between cancer and macrophages via CCR2 and CX3CR1 was an important mechanism that drives lung cancer development and metastasis." (PMID 38786066, 2024). "MLN1202, a monoclonal antibody targeting CCR2, has been explored in bone metastasis of cancer and inflammatory conditions, effectively blocking the migration of CCR2+ cells into the TME." (PMID 39286635, 2024). "JAK/STAT and PI3K/AKT signaling pathways are activated during the binding of CCL2 to CCR2, which ultimately leads to an increase in the proliferation of cancer cells." (PMID 37325423, 2023). "Numerous types of research have been done to study the effect of CCR2_CCL2 signaling pathway inhibition in preventing cancer progression." (PMID 37325423, 2023). "CCR2 High monocytes guided through the CCR2-CCL2 axis within the tumors facilitate cancer cell survival through VEGF production." (PMID 36357631, 2023). "Various cell types, including DC, endothelial cells, monocytes, macrophages, Th1 cells, basophils, NK cells and various cancer cells express CCR2, which binds to CCL2." (PMID 37170733, 2023). "In view of the multiple roles of CCL2/CCR2 signalling in cancer, a number of anticancer treatment studies have been carried out on this signalling axis." (PMID 35999359, 2023).
cancer (continued). "The binding of CCL2 to CCR2 promotes the recruitment of macrophages to metastatic sites, thereby accelerating the dissemination and expansion of cancer cells." (PMID 38180104, 2023). "According to these documents, the CCR2_CCL2 signaling pathway plays a key role in the development of cancer, which makes the CCR2 receptor an important and potential therapeutic target in cancer treatment." (PMID 37325423, 2023). "Based on this evidence, CCR2 has been expected to be a potential therapeutic target for human cancer." (PMID 36810973, 2023). "Since the CCR2_CCL2 signaling pathway can increase the survival of cancer cells, proliferation, and metastasis, CCR2 is considered a potential therapeutic target in cancer treatment." (PMID 37325423, 2023). "Although STAT3 is demonstrated to be a transducer of other cytokines, CCR2 knockout study has shown to reduce PD-L1 expression in cancer cells." (PMID 37792212, 2023). "Still, our comprehensive bioinformatics analysis of cancer–nerve crosstalk-associated genes in SKCM constructed a valuable prognostic model based on eight genes (GRIN3A, CCR2, CHRNA4, CSF1, NTN1, ADRB1, CHRNB4, and CHRNG) and common clinical characteristics." (PMID 37404751, 2023). "CCL2-CCR2 signaling controls the supply of circulating inflammatory monocytes and inhibiting CCR2 keeps monocytes in bone marrow, reducing TAMs at cancer sites." (PMID 37965573, 2023). "Among these chemokines, CCL2, together with its main receptor, CCR2, can increase cancer progression." (PMID 37325423, 2023). "A recent study demonstrated that cancer cell CCR2 orchestrates suppression of the adaptive immune response." (PMID 38133335, 2023). "Inflammatory monocytes (CCR2+Ly6Chi) are an important population infiltrating into primary and metastatic tumor sites for cancer progression, especially through their interaction with the endothelium to affect angiogenesis and vascular permeability." (PMID 35267547, 2022). "Ubiquitous expression of CCL2 and its receptor CCR2 has been identified in patient samples from various types of cancers." (PMID 35267547, 2022). "It has been revealed that CCR2 is widely expressed in a broad range of cell types, including monocytes, endothelial cells, DCs,95 and various cancer cells and the upregulation of CCR2 is related to advanced cancer, metastasis, and relapse." (PMID 35702353, 2022). "Together, these studies have shown the efficacy of CCR2 targeting agents in reducing the frequency of MDSCs and improving the overall survival of cancer patients." (PMID 35122833, 2022). "CCL2 secreted by senescent hepatocytes recruits CCR2+ myeloid cells, which then become mature and eliminate senescent cells and thereby suppress cancer development." (PMID 35674109, 2022). "CCL2 expression by cancer cells promotes the recruitment of TAM expressing CCR2 to facilitate cancer cell anchorage in the bone." (PMID 35677054, 2022). "Due to the contribution of the CCL2/CCR2 and CXCL1/CXCR2 axes to the pathology of various cancers, there have been attempts to develop CCR2 and CXCR2 antagonists, anticipating therapeutic benefits from CCR2 and CXCR2 inhibition." (PMID 36403057, 2022). "Because of its primary role in macrophage chemotaxis, the CCL2/CCR2 chemokine signalling pathway has been frequently studied in mouse models of cancer as well as in cancer patients, with translation into the clinic." (PMID 36241867, 2022). "Consistent with our observation, many studies have reported a role for the cancer-secreted CCL2 in recruiting CCR2+ MDSCs to the TME." (PMID 34874922, 2022). "Macrophages in the PDAC microenvironment are recruited by C-C chemokine receptor type 2 (CCR2) and colony-stimulating factors and secrete GDNFs to promote cancer migration and nerve invasion." (PMID 36077804, 2022). "CCR2 is CC chemokine receptor 2, and CCR2 signal transduction in cancer cells can coordinate the suppression of immune response." (PMID 35938142, 2022).
cancer (continued). "CCR2-targeting strategies have shown efficacy in cancer patients by reducing infiltration of monocytes in the tumors." (PMID 35122833, 2022). "PLG regulates macrophage invasion, MMP proteins, or CCL2/CCR2 axis and is involved in cancer cell proliferation, migration, growth, and metastasis." (PMID 34861103, 2022). "To decipher the molecular mechanism as to how CCL2 enhances HNSCC cell migration, we have intervened in CCR2 and CCR4, which were reported to be associated with cancer cell progression." (PMID 35177591, 2022). "It has been reported that CCR2 expression in cancer cells accelerates PNI in the in vitro tumor-nerve co-culture invasion assays." (PMID 36077602, 2022). "The interaction of stroma-secreted CCL2 with CCR2+ MDSCs is essential for the complex crosstalk between cancer cells, stromal cells, and MDSCs; thus, it promises to constitute an attractive target for OSCC treatment." (PMID 34874922, 2022). "CCL2, a crucial chemokine in TME, functions mainly through binding to its receptor CCR2 and recruit macrophage and monocyte, which promotes cancer progression and metastasis." (PMID 35978854, 2022). "The CCL2/CCR2 axis has been proposed as a potential target for decreasing MDSCs recruitment and improving cancer treatment." (PMID 34874922, 2022). "The role of CCR2-CCL2 interactions in directing the migration of CCR2+ monocytic cells has been mostly studied for two types of diseases: inflammatory autoimmune diseases, and cancer." (PMID 34944943, 2021). "Based on the Wilcoxon rank sum test, we found that the expression of CCR2 in cancer samples was conspicuously lower compared to normal ones." (PMID 34251980, 2021). "Much of the research investigating monocyte/macrophage recruitment strategies as targets for anti-cancer therapy have centered around the CCL2/CCR2 axis given that CCR2 is overexpressed by many tumors and enhances monocyte recruitment into the TME." (PMID 33924237, 2021). "Although CCR2 antagonism in cancer is predominantly discussed in the context of solid tumors, the CCL2/CCR2 axis is also implicated in blood cancers." (PMID 34804061, 2021). "The CCR5/CCL5 axis, apart from having a similar immunomodulatory role to CCR2/CCL2, has also been implicated in cancer progression and metastasis as well as a marker of poor prognosis in several cancers." (PMID 33546207, 2021). "Therapeutic strategies targeting the CCL2‐ CCR2 axis have also shown promising effects, enriching our approaches for fighting against cancer." (PMID 34464477, 2021). "Radiotherapy in cancer induces the recruitment of CCR2+ Tregs that contribute to treatment resistance." (PMID 34804061, 2021). "Both CCR2 inhibitors and anti-CCL2 monoclonal antibodies have been used in pre-clinical murine models to disrupt this CCL2/CCR2 interaction, showing efficacy both on their own and in combination with other anti-cancer therapies." (PMID 34209703, 2021). "The expression levels of CCL2 and CCR2 can be regarded as a predictor of poor prognosis in patients with cancer." (PMID 34464477, 2021). "CAF associated FAK can regulate expression of some chemokines like Cc16 and Cc112, and help metabolism in cancer cell through malignant Ccr1/Ccr2 and PKA activation." (PMID 34821729, 2021). "The axis of chemokine CCL-2 and its receptor CCR2 are identified as the elements in cancer–nerve crosstalk, forming a tumor microenvironment that facilitates the PNI." (PMID 34441243, 2021). "CCL2 is mainly secreted by Schwann cells that first arrive at the sites of cancer cells and bind to the CCR2, promoting proliferation, migration, invasion, and epithelial–mesenchymal transition (EMT)." (PMID 34441243, 2021). "Treatment with a CCR2 antagonist reduced the liver tumor volume, inhibited the abdominal dissemination and metastasis of cancer cells and reduced the recurrence of HCC after surgery." (PMID 34804061, 2021).
cancer (continued). "CCL2/CCR2 signaling played a key role in the stimulation and sustainment of cancer cell proliferation, invasion migration, and metastasis, and induction of deleterious inflammation and angiogenesis." (PMID 34251980, 2021). "We also explore unique signaling, TME and stromal targeting via novel small molecule inhibitors, which target KRAS, FAK, CCR2/CCR5, CXCR4, PARP and cancer-associated fibroblasts." (PMID 34771675, 2021). "Contribution of CCR2-mediated recruitment of monocytes in cancer metastasis is nicely demonstrated in a study with monocyte transfer." (PMID 34804061, 2021). "The discovery of 747 provided a novel perspective on the development of CCR2 antagonists and enriched the therapeutic options against cancer." (PMID 34464477, 2021). "Here, we demonstrated that repeated i.t. injection of INCB3344 exerted anti-allodynic effects, as previously observed in neuropathic, postoperative, and cancer-induced bone pain models using anti-CCL2 antibodies or small molecule antagonists of CCR2." (PMID 33757529, 2021). "We confirmed, in multiple cancer types, that the combination anti-PD-1 and CCR2-targeted therapy leads to enhanced efficacy compared to either agent alone." (PMID 33247183, 2020). "Further understandings are needed to clarify the value of CCL2/CCR2 as a prognostic factor in many different cancer types." (PMID 31991604, 2020). "There is also compelling evidence for the targeting of CCL2/CCR2 in the treatment of various cancers." (PMID 33247183, 2020). "After cocultivation with HeLa and ME-180 cells, the expression of CCL2 in SCs and its receptor CCR2 on the membrane of cancer cells both increased." (PMID 32064233, 2020). "In particular, therapeutic blockade of CCL2-CCR2 interaction by using CCL2 neutralizing antibodies or CCR2 antagonist has demonstrated promising antitumor efficacies in several preclinical cancer models." (PMID 32849585, 2020). "Previous studies have revealed that CCL2 secreted by the nerves facilitates pancreatic ductal adenocarcinoma invasion by binding to its receptor (CCR2) expressed on the membrane of cancer cells or macrophages." (PMID 32064233, 2020). "In lung cancer cells, endothelial CCR2 expression is reported to be an important factor for cancer cell extravasation and pulmonary metastasis as well." (PMID 33297571, 2020). "In metastatic colorectal cancer liver metastatic model mice, administration of CCR2 inhibitor improves the chemotherapy response and prolongs overall survival of cancer-bearing mice." (PMID 33297571, 2020). "Firstly, by cell to cell contact through CD47 (cancer cell) and SIRPα (macrophage) binding, CCR2, or CX3CR1 chemokine receptors; Secondly, through soluble factors or exosomes loaded in IL-10." (PMID 32477352, 2020). "CCL2 induces cancer cell migration and contributes to the early stages of metastasis by interacting with CCR2 expressed on cancer cells." (PMID 33297571, 2020). "CCL2 and its receptor CCR2 were reported to play crucial roles in cancer metastasis, accelerate cancer cell growth, and promote their colonization at metastasis sites." (PMID 32064233, 2020). "The chemokine CCL2 and its main receptor CCR2 have been receiving particular interest on their roles in cancer pathogenesis." (PMID 32471499, 2020). "Inhibition or blockade of the CCL2/CCR2 signaling axis has thus been an area of interest for cancer therapy." (PMID 33247183, 2020). "CCR2 has been found to be expressed by multiple cell types including monocytes, dendritic cells (DCs), endothelial cells, and cancer cells." (PMID 32471499, 2020). "CCL2, produced by both cancer and stromal cells, preferentially binds to CCR2, which is expressed to varying degrees in a wide range of organs and tissues including blood, brain, heart, kidney, liver, lung, ovary, pancreas, spinal cord, spleen, and thymus." (PMID 33247183, 2020).
cancer (continued). "Our major focus has been on the control of cancer cell Ccr1 and Ccr2 in CAF-FAK regulation of malignant cell metabolism as we detected the most significant increases in their ligands, Ccl6 and Ccl12, respectively." (PMID 32157087, 2020). "Results from our group demonstrate the therapeutic potential of CCR2 as a novel target in treatment of PCa, and possibly other types of cancer, particularly in obese state with a host CCL2-stimulated environment." (PMID 32471499, 2020). "Mechanistically we demonstrate that FAK-depletion in CAFs increases chemokine production, which via CCR1/CCR2 on cancer cells, activate protein kinase A, leading to enhanced malignant cell glycolysis." (PMID 32157087, 2020). "The function of CCR2 has been demonstrated to participate in several processes of cancer progression." (PMID 31501414, 2019). "CCR2 is the most important chemokine receptor in the recruitment of macrophages in cancer; genetic deletion of CCR2 results in less infiltration of macrophages in mouse xenografts." (PMID 31781681, 2019). "In conclusion, this study identifies CCR2 as a top upregulated chemokine receptor in regorafenib-resistant cancer cells." (PMID 31501414, 2019). "Interference with the CCL2/CCR2 axis exerts antitumoral activity in many cancers for the reduced recruitment of monocytes with pro-tumorigenic and pro-metastatic activities." (PMID 30894861, 2019). "CCL2 and CCR2 are currently therapeutic targets of interest for anti-cancer treatment and inflammatory diseases." (PMID 31208996, 2019). "Further in vitro and in vivo clarifications are required to understand the targeting mechanism of the CCL2/CCR2 pathway using CR and its nano-combination with AV in cancer therapy." (PMID 31350989, 2019). "Osteoblastic CCL2 induced the migration of CCR2-expressing cancer cells and in this manner contributed to bone metastasis formation." (PMID 31572390, 2019). "The rationale of the current study is to explore the sensitizing capability of the DOX-treated cancer cells using the anticancer agents; bevacizumab (avastin; AV) and CCR2 inhibitor (CR) in their free- and nano-formulations." (PMID 31350989, 2019). "The combination of CCL2 or CCR2 with antigen CA 15-3 resulted in an increase in the NPV in all stages of cancer." (PMID 30151375, 2018). "In mice that have received the subcutaneous injection of LLC cancer cells, treatment with a CCR2 antagonist (RS504393) inhibits the establishment of lung metastatic foci." (PMID 30483271, 2018). "The disruption of CCL2/CCR2 chemokine signaling has been shown to suppress cancer cellviability and metastasis." (PMID 28424406, 2017). "Our data indicated that targeting CCR2 with an antagonist would be an attractive strategy to ameliorate cancer cell viability, motility and invasion in CCR2-positive NSCLC patients." (PMID 28424406, 2017). "Increasing evidence points to the vital effects of CCL2/CCR2 on the proliferative and metastatic properties of cancer cells." (PMID 28424406, 2017). "Further clarification is required to understand the targeting of the CCL2/CCR2 pathway in cancer therapy." (PMID 28424406, 2017). "Herein, we examined the potential use of the CCR2-specific small molecule inhibitor (CAS 445479-97-0) in cancer therapy." (PMID 28424406, 2017). "The disruption of CCL2/CCR2 chemokine signaling has been shown to suppress cancer cell proliferation, migration and invasion." (PMID 28424406, 2017). "CCl2 together with its cognate CCR2 play key roles in cancer metastasis by sustaining cancer cell proliferation and survival, stimulating cancer cell migration and invasion, and inducing deleterious inflammation and angiogenesis." (PMID 28487672, 2017).